RN7SL426P (RNA, 7SL, cytoplasmic 426, pseudogene)
Gene: Miscellaneous RNA gene on chromosome 17 (21,229,334 to 21,229,628, reverse strand). Ensembl gene ENSG00000263815.
Homologues: Orthologues: chimpanzee Metazoa_SRP (99% identical), macaque Metazoa_SRP (92% identical), guinea pig Metazoa_SRP (59% identical). Paralogues in human: RN7SL2 (86% identical), RN7SL1 (85% identical), RN7SL3 (83% identical), RN7SL126P (82% identical), RN7SL296P (81% identical), RN7SL18P (81% identical), RN7SL408P (81% identical), RN7SL650P (81% identical), RN7SL664P (81% identical), RN7SL679P (81% identical), Metazoa_SRP (81% identical), RN7SL145P (81% identical), and 699 more.